U6 (U6 spliceosomal RNA )
Synonyms: LOC124905168
Gene: Small nuclear RNA gene on chromosome 22 (15,273,855 to 15,273,961, forward strand). Ensembl gene ENSG00000276138.
Gene Ontology:
Molecular function: U4 snRNA binding
Biological process: formation of quadruple SL/U4/U5/U6 snRNP; spliceosomal tri-snRNP complex assembly
Cellular component: U4/U6 x U5 tri-snRNP complex; U6 snRNP
Homologues: Orthologues: macaque U6 (91% identical), dog U6 (64% identical), rabbit U6 (64% identical), pig U6 (61% identical), rabbit U6 (59% identical). Paralogues in human: RNU6-458P (100% identical), U6 (98% identical), RNU6-1293P (97% identical), RNU6-156P (97% identical), RNU6-1132P (95% identical), RNU6-614P (95% identical), RNU6-721P (94% identical), U6 (94% identical), RNU6-978P (93% identical), RNU6-1207P (92% identical), RNU6-811P (92% identical), RNU6-452P (87% identical), and 1289 more.